PABPC3 (poly(A) binding protein cytoplasmic 3)
Description:
Binds the poly(A) tail of mRNA. May be involved in cytoplasmic regulatory processes of mRNA metabolism. Binds poly(A) with a slightly lower affinity as compared to PABPC1.
Synonyms: PABP3; PABPL3; tPABP
Tractability: PROTAC: UniProt records ubiquitination sites on it; ubiquitination databases record sites on it.
Gene: Protein-coding gene on chromosome 13 (25,096,136 to 25,099,254, forward strand). Ensembl gene ENSG00000151846.
Subcellular location: Cytoplasm
Subcellular location (Human Protein Atlas): Cytosol
Gene Ontology:
Molecular function: poly(A) binding; protein binding; mRNA 3'-UTR binding; poly(U) RNA binding; nucleic acid binding; RNA binding
Biological process: mRNA metabolic process
Cellular component: extracellular exosome; cytoplasm; cytoplasmic stress granule; cytosol; nucleus; ribonucleoprotein complex
Genetic constraint (gnomAD): Loss-of-function variants: 43 observed, 42.45 expected, observed/expected ratio (o/e) 1.01, 90% interval 0.79 to 1.31. The upper end of that interval is the gene's LOEUF score, 1.31, which puts it in group 5 of 6, group 1 being the genes least tolerant of losing a copy. Missense variants: 781 observed, 800.09 expected, observed/expected ratio (o/e) 0.98, 90% interval 0.92 to 1.04. Synonymous variants: 220 observed, 267.4 expected, observed/expected ratio (o/e) 0.82, 90% interval 0.74 to 0.92.
Homologues: Orthologues: chimpanzee PABPC3 (98% identical), macaque PABPC3 (94% identical), rat Pabpc6 (79% identical), mouse Pabpc6 (78% identical), mouse Pabpc2 (75% identical), rat Pabpc2 (71% identical). Paralogues in human: PABPC1 (93% identical), PABPC4 (73% identical), PABPC1L (65% identical), PABPC4L (40% identical), PABPC5 (36% identical), PABPC1L2A (23% identical), PABPC1L2B (23% identical), RBMS3 (18% identical), RBMS1 (17% identical), RBMS2 (16% identical), SYNCRIP (15% identical), HNRNPR (15% identical), and 12 more.
Diseases named in the same sentence as PABPC3 in open-access papers:
PABPC3 is named in the same sentence as 18 diseases in open-access papers, as found by Europe PMC text mining. Sharing a sentence is not in itself a finding about the gene and the disease. The quoted sentences say what the papers report.
breast carcinoma (4 papers, 2018 to 2022). "Previous studies reported that WES reveals high-risk frameshift mutations and somatic mutations for PABPC3 in breast cancer patients and malignant ovarian germ cell tumors, respectively." (PMID 35038288, 2022). "PABPC3 was found to have germline mutation in a breast cancer cohort of Tunisian females." (PMID 32731431, 2020). "PABPC3 has been reported to be a breast cancer candidate gene that may be associated with breast cancer." (PMID 33224957, 2020). "PABPC3 seems to be another interesting breast cancer candidate gene that may be associated with breast cancer in an ethnic specific manner as it has been reported in another North African population." (PMID 29879995, 2018). "Except PABPC3, genes identified in this Tunisian breast cancer family have not been reported in other breast cancer exome sequenced families, suggesting a family specific genetic predisposition to the disease." (PMID 29879995, 2018).
follicular thyroid cancer (2 papers, 2020). "WES analyses of six follicular thyroid cancer cell lines revealed PABPC3 to be a recurrently mutated cancer driver gene." (PMID 32373524, 2020). "Except for PABPC1, PABPC3 was also found as a cancer driver gene in follicular thyroid cancer." (PMID 32454908, 2020).
central precocious puberty (1 paper, 2021). "Here we reported that the three members of PABPs, including PABPC1, PABPC3 and PABPC4, were identified as novel substrates for MKRN3, whose deletion or loss-of-function mutations were genetically associated with human central precocious puberty (CPP)." (PMID 33744966, 2021).
head and neck cancer (1 paper, 2019). A primary or metastatic malignant neoplasm affecting the head and neck. "Relatively frequent mutations were also detected in several other IntOgen-defined cancer drivers such as MGA, PABPC3, NR4A2, NCOR1 and MACF1; of these PABPC3, NR4A2, NCOR1 and MACF1 are detected as mutational cancer drivers in head and neck cancer in IntOgen." (PMID 31427592, 2019).
hepatocellular carcinoma (1 paper, 2020). A malignant tumor that arises from hepatocytes. "Through transcriptome sequencing of human hepatocellular carcinoma (HCC) samples, six genes—TSC1, TSC2, PABPC3, HIF1α, RB1CC1 (ATG17), and RPS6KA3 (RSK2)—were found to be associated with HBV infection." (PMID 33059752, 2020).
infertile (1 paper, 2023). "Importantly, PABPC1, PABPC1L, and PABPC3 expressions are perturbed in infertile men." (PMID 37176068, 2023).
melanoma (1 paper, 2020). A malignant, usually aggressive tumor composed of atypical, neoplastic melanocytes. "We found that HRNR, KMT2C, and PABPC3 were among the most frequently mutated genes in cutaneous SCCs and melanomas." (PMID 32188867, 2020).
metastatic tumors (1 paper, 2025). "PABPC3 was highly expressed in metastatic tumors, with much lower expression in primary tumors, suggesting that PABPC3 is a potential key driver of ovarian cancer metastasis." (PMID 41249135, 2025).
osteonecrosis (1 paper, 2022). A none disease characterized by death of bone tissue due to a lack of blood supply. "Our finding suggests that KRT18 and PABPC3 may be implicated in MRONJ pathophysiology, and that they may be used as a therapeutic target in the treatment of osteonecrosis." (PMID 35456240, 2022).
ovarian carcinoma (1 paper, 2025). A malignant neoplasm originating from the surface ovarian epithelium. "Our in vitro findings indicated that PABPC3 influences ovarian cancer cell metastasis through modulation of tight junctions." (PMID 41249135, 2025). "Our results demonstrated that ovarian cancer cells with elevated PABPC3 expression exhibited decreased drug sensitivity to chemotherapeutic agents and decreased sensitivity to PARP inhibitors." (PMID 41249135, 2025). "In conclusion, this study underscores the pivotal role of PABPC3 in ovarian cancer metastasis and patient prognosis, highlighting it as a potential therapeutic target for improving clinical outcomes." (PMID 41249135, 2025). "Functional experiments reveal that PABPC3 knockdown markedly inhibits ovarian cancer cell proliferation and migration, whereas its overexpression exerts the opposite effects." (PMID 41249135, 2025). "In this study, through single-nucleus RNA sequencing and analysis of clinical samples, we identify PABPC3 as a key regulator of ovarian cancer metastasis and patient survival." (PMID 41249135, 2025). "Here, we further investigated the effects of PABPC3 on the ovarian cancer cell line OVCAR3 and SKOV3 by siRNA." (PMID 41249135, 2025). "Survival analysis using various databases was performed for PABPC3 and indicated that the higher PABPC3 expression in ovarian cancer correlates with shorter overall survival." (PMID 41249135, 2025). "In this study, we demonstrate that PABPC3 levels significantly influence the migratory and proliferative capacity of ovarian cancer cells." (PMID 41249135, 2025). "Through in vitro and in vivo experiments, we confirmed that high PABPC3 expression enhances the migratory capacity of ovarian cancer cells, indicating that PABPC3 plays a crucial role in ovarian cancer metastasis." (PMID 41249135, 2025). "While PABPC3’s specific effects on cell proliferation and metastasis in ovarian cancer patients remain unexplored." (PMID 41249135, 2025). "Conversely, silencing PABPC3 in cells resulted in increased CLDN1 levels, further suggesting that PABPC3 promotes ovarian cancer metastasis." (PMID 41249135, 2025). "To further examine the impact of PABPC3 overexpression in ovarian cancer cells, we established a stable PABPC3-overexpressing cell line, referred to as Flag-PABPC3, in the ID8 cell line via lentiviral transduction." (PMID 41249135, 2025). "Follow-up studies of ovarian cancer patients indicated that those with high PABPC3 expression had a higher mortality rate post-treatment compared to patients with low expression, further supporting the role of PABPC3 in drug sensitivity." (PMID 41249135, 2025). "Our findings suggest that PABPC3 expression levels in tumor cells may influence the tumor microenvironment during ovarian cancer metastasis, thereby promoting metastatic spread." (PMID 41249135, 2025). "It was indicated that PABPC3 may promote ovarian cancer metastasis and could represent a viable therapeutic target." (PMID 41249135, 2025). "Given that radiotherapy is another effective cancer treatment, we further tested whether PABPC3 overexpression confers radioresistance in ovarian cancer." (PMID 41249135, 2025). "Similarly, following tail vein injection of ovarian cancer cells, tumors were primarily localized to the lung region, and mice in the PABPC3 overexpression group exhibited higher fluorescence intensity, indicating increased metastasis capacity in vivo." (PMID 41249135, 2025). "Therefore, PABPC3 represents a promising therapeutic target for ovarian cancer treatment." (PMID 41249135, 2025). "In this study, we also investigated the relationship between PABPC3 levels and chemotherapy resistance and PARP inhibitors, which have been commonly used to treat ovarian cancer in recent years." (PMID 41249135, 2025). "Our experiments revealed that PABPC3 overexpression does not alter the sensitivity of ovarian cancer cells to radiation." (PMID 41249135, 2025).
ovarian carcinoma (continued). "To investigate the impact of PABPC3 on drug sensitivity, we treated ID8 and Flag-PABPC3 cell lines with the common first-line chemotherapeutic agents, including carboplatin and paclitaxel, as well as the PARP inhibitor Olaparib, which has been increasingly used to treat ovarian cancer." (PMID 41249135, 2025).
ovarian germ cell tumor (1 paper, 2022). A neoplasm that arises from the ovary and originates from germ cells. "PABPC3 was recently listed among the most mutated genes in malignant ovarian germ cell tumors (n = 10)." (PMID 36229065, 2022).
cancer (7 papers, 2016 to 2025). A tumor composed of atypical neoplastic, often pleomorphic cells that invade other tissues. "By integrating data from the TCGA Pan-Cancer cohort, we identified 17 signature genes significantly correlated with overall survival (p < 0.01), with PABPC3 showing the most substantial difference." (PMID 41249135, 2025). "There are no reports on the role of PABPC3 in cancer, and this is the first time that an association to cancer is described." (PMID 29844869, 2018).
tumor (7 papers, 2014 to 2025). "Mechanistically, PABPC3 promotes tumor metastasis by modulating the expression of CLDN1, a critical component of tight junctions." (PMID 41249135, 2025). "Some of the identified prognostic DE RBPs have been reported associated with tumor progression, such as RBM47, LUZP4, AFF3, PPARGC1A, PPARGC1B, PABPC3, and PNLDC1." (PMID 33224957, 2020). "Several genes (including BCR, PCLO, ATXN3, PABPC3, and FADS6) were mutated in two or more PDX tumours." (PMID 33144587, 2020). "Collectively, these results further suggested the essential role of PABPC3 in tumor metastasis." (PMID 41249135, 2025). "Integrating these findings with public database survival analyses, we identified that PABPC3 expression levels may correlate with tumor metastasis and patient prognosis." (PMID 41249135, 2025). "It suggests that PABPC3 may contribute to tumor resistance and could serve as a potential therapeutic target." (PMID 41249135, 2025). "The staining indicated that the Flag-PABPC3 group had larger tumor areas." (PMID 41249135, 2025). "Meanwhile, previous studies have shown that PABPC3 can drive tumor progression in osteosarcoma, although its role in tumor metastasis remains unclear." (PMID 41249135, 2025). "Moreover, both in vitro and in vivo experiments demonstrated that high PABPC3 expression enhances tumor cell migration, compromises tight junction integrity, and decreases drug sensitivity, highlighting PABPC3 as an essential factor in both metastasis and drug sensitivity." (PMID 41249135, 2025). "Among the 5,291 coding somatic mutations found in an aggregate of 240 matched tumour/normal samples, we found 26 overlapping variants in SH-SY5Y inside 24 genes among which 9 were rare amino-acid changing mutations inside 7 genes (ALK, FOXD4L1, HLA-DRB1, NBPF10, NBPF14, PABPC3, TEKT4)." (PMID 25528190, 2014). "Of these, five were present in at least one tumor from each cohort: IGLL5 p.L28M, MTMR1 p.R389Q, MYD88 p.S206C, PABPC3 p.K231E." (PMID 40634688, 2025). "Taken together, these findings indicate that PABPC3 overexpression enhances metastatic capacity in vivo, with reduced expression of Claudin family members CLDN1 suggesting decreased tight junction integrity, which may be a potential reason for tumor metastasis." (PMID 41249135, 2025).
cardiovascular diseases (1 paper, 2020). "Analyzed genes were associated with cardiovascular diseases and risk factors (TBC1D22A, WNK1), bone mineral density (HDAC5), body weight (PABPC3), glycerophospholipid metabolism (CDS2), Notch signaling (HDAC5), RNA transport and degradation (PABPC3)." (PMID 32344947, 2020).
neurogenetic diseases (1 paper, 2017). "As the examples, copy number change in NBPF10 is associated with multiple developmental and neurogenetic diseases, PABPC3 is involved in regulation of mRNA stability and translation initiation, and NPIPB11 is involved in forming nuclear pore complex." (PMID 28076423, 2017).
PABPC3 also shares sentences with these, for which no sentence is quoted: Alzheimer disease (1 paper); glioma (1); malignant ovarian germ cell tumors (1).